HR (HR lysine demethylase and nuclear receptor corepressor)
Diseases named in the same sentence as HR in open-access papers (continued):
Sharing a sentence is not in itself a finding about the gene and the disease.
breast cancer (continued). "Based on this finding, ribociclib combined with fulvestrant may be a new first- or second-line treatment option for postmenopausal women with HR+/HER2− advanced breast cancer." (PMID 30595753, 2018). "According to these biomarkers, BC can be categorised into at least four subtypes: hormone receptor‐positive (HR+)/HER2‐negative (HER2−), HR+/HER2‐positive (HER2+ or HER2‐enriched), HR−/HER2+ and triple‐negative breast cancer (TNBC)." (PMID 41555955, 2026). "However, HR+/HER2+ breast cancer possesses distinct molecular biological characteristics, and only a small number of patients with HR+/HER2+ breast cancer have been enrolled in previous models, making them less helpful for clinical decision‐making in these patients." (PMID 38185807, 2024). "The BC subtype was available in 641 cases: 264 patients (41.2%) were HR+/HER2−, 116 (18.1%) were HER2+, and 261 (40.7%) had triple-negative breast cancer (TNBC)." (PMID 39741970, 2024). "In addition, the vast majority of HR+/HER2+ breast cancer patients have received trastuzumab, and over half have been treated with anthracyclines; both of these therapies have some degree of cardiotoxicity, which may further be enhanced by OFS drugs." (PMID 38185807, 2024). "Although previous studies did not present the FNRs of these procedures according to the subtypes, we expect that these surgical procedures may improve the accuracy of axillary staging in non-complete MRI responders with HER2+ or TNBC or in those with HR+ HER2− breast cancer." (PMID 38632652, 2024). "Indeed, the addition of palbociclib, ribociclib, or abemaciclib to endocrine therapy in first or subsequent lines for patients with HR+/HER2- advanced breast cancer has demonstrated a clinically significant survival benefit, thus becoming a standard of care for this subset of patients." (PMID 36902563, 2023). "The OPTIMA (Optimal Personalized Treatment of Early Breast Cancer Using Multi-Parameter Analysis) de-escalation, partially blinded, clinical trial will evaluate the ability of the Prosigna PAM50 test to tailor adjuvant therapy for HR+/HER2− high-clinical risk BC patients." (PMID 35203458, 2022). "Similarly, in the adjuvant treatment of early breast cancer, oral SERDs are being studied against AIs or physicians’ choice as in the Lidera Breast Cancer Study (giredestrant) or tamoxifen as in AMEERA-6 (amcenestrant) in HR + /HER2 − stages I–II early breast cancers." (PMID 36229710, 2022). "The treatment strategy of breast cancers has been modified by the identification of different subgroups of this heterogenous disease and emergence of resistance to endocrine therapy till today remains a matter of grave concern in patients with HR+/HER2− advanced/metastatic breast cancer." (PMID 34376758, 2021). "However, recent substantial advances have been made in the management of HR+/HER2‒ advanced breast cancer (ABC) with the advent of targeted therapies, such as cyclin-dependent kinase 4/6 (CDK4/6) inhibitors, resulting in significant improvements in survival outcomes versus endocrine therapy alone." (PMID 34698970, 2021). "Thus, greater use of ET plus a CDK4 & 6 inhibitor as initial therapy for advanced disease in women with HR+/HER2− advanced breast cancer may have the potential to maintain/improve patient HRQoL." (PMID 32894087, 2020). "A possible explanation may be the lack of specific treatment guidelines, which will require prospective randomized studies demonstrating the first-line combination of hormonal therapy and anti-Her2 therapy is superior to chemotherapy and anti-HER2 in metastatic HR+/HER+ breast cancer patients." (PMID 31792304, 2019). "Effective communication and planning are essential when guiding patients through the complex and often prolonged treatment journey for HR+, HER2− early breast cancer." (PMID 40862813, 2025).
breast cancer (continued). "The most common breast cancer subtypes express hormone receptors, including progesterone (PR) and estrogen (ER), and are classified as hormone receptor–positive, HER2-negative (HR+/HER2−) tumors, also known as luminal A and B subtypes." (PMID 41550427, 2025). "•Selection of postmenopausal patients with HR+/HER2- N0, breast cancer for gene expression profiling is imprecise." (PMID 40347583, 2025). "The addition of cyclin-dependent kinase (CDK) 4/6 inhibitors to endocrine therapy (ET) has improved the outcomes of patients with hormone receptor-positive (HR+) and human epidermal growth factor receptor 2-negative (HER2−) advanced breast cancer." (PMID 40161091, 2025). "CDK4/6 inhibitors have also demonstrated improved invasive disease-free survival (iDFS) in patients with HR+, HER2− early breast cancer." (PMID 40862813, 2025). "The primary aim of this study was to identify effective prognostic biomarkers for breast cancer (BC), with a specific focus on hormone receptor-positive, HER2-negative (HR+/HER2-) breast cancer, which represents a major subset of BC cases." (PMID 40002266, 2025). "The most common molecular types of breast cancer were HR+/HER2- (59%) and triple-negative (23%) breast cancer." (PMID 37314691, 2024). "c-MET overexpression was observed in 4.7% (17/358), 3.8% (4/104), 7.1% (7/98), and 13.6% (22/162) of the primary sites in HR+/HER2−, HR+/HER2+, HER2-enriched, and Triple-negative breast cancer samples, respectively." (PMID 38238761, 2024). "In the phase III MONALEESA-3 trial, the efficacy of ribociclib plus fulvestrant was compared with that of fulvestrant on the patients with HR+, HER2− advanced breast cancer and included both first line and second-line patients." (PMID 38339303, 2024). "Patients with the hormone receptor–positive (HR+), human epidermal growth factor receptor 2–negative (HER2−) molecular subtype are known to be the largest subpopulation of breast cancer patients (> 70%)." (PMID 39177931, 2024). "18,037 HR+, HER2−, cN+ stage II and stage III breast cancer patients within eleven studies received neoadjuvant treatments." (PMID 39742366, 2024). "Hormone receptor-positive (HR+) and human epidermal growth factor receptor 2-negative (HER2-) breast cancer represent a common subtype, and endocrine therapy (ET) is one of the primary treatment modalities." (PMID 39640578, 2024). "It is indisputable that CDK 4/6 inhibitors are the primary treatment for patients with HR+, HER2-advanced breast cancer." (PMID 39640578, 2024). "This study provides insight into the efficacy of NET for cN+, HR+, HER2− breast cancer; however, it has several limitations." (PMID 39742366, 2024). "In this meta-analysis, we found that HR+, HER2−, cN+ breast cancer patients undergoing NET are less likely to achieve node pCR (8.9%) than patients receiving NAC (14.9%)." (PMID 39742366, 2024). "We report a rare case of a 52-year-old female with HR+, HER2- metastatic breast cancer who developed vitiligo-like depigmentation following palbociclib treatment." (PMID 39006687, 2024). "Patients with hormone receptor-positive (HR+), HER2-negative (HER2−) breast cancers have the lowest response to neoadjuvant therapy of all subtypes." (PMID 39742366, 2024). "Its versatility in treating various breast cancer subsets (HER2+, HR+/HER2−, and triple-negative) and extended treatment duration underscore its potential positive impact on breast cancer therapy." (PMID 39272947, 2024). "In total, 27,569 HR+, HER2− stage II and III breast cancer patients were included from eleven studies." (PMID 39742366, 2024). "Its clinical utility in early breast cancer has been demonstrated by both the POETIC and WSF ADAPT HR+/HER2- trials, and this is what we aim to further explore through trials such as that proposed in our survey." (PMID 39595037, 2024).
breast cancer (continued). "Here, we demonstrate for the first time that ADAM8, a critical driver of tumor growth and spread, is expressed in about one third of all breast tumors, extending our published findings on TNBC to HR+ and HER2+ breast cancer." (PMID 37568162, 2023). "At present, anti-her-2 therapy and anti-HR + therapy have significantly improved the prognosis of HER-2 overexpression and HR + breast cancer, while triple-negative breast cancer (TNBC) lacks therapeutic targets." (PMID 37012515, 2023). "Half of referred patients were HR+/HER2− BC, with 39% triple negative breast cancer (TNBC)." (PMID 36826152, 2023). "In clinical trials testing abemaciclib in patients with hormone-receptor-positive (HR+), HER2-negative (HER2-) advanced breast cancer, diarrhea is a very common adverse event (occurring in approximately 85% of patients, any grade)." (PMID 36902563, 2023). "Genomic tests are a useful tool for adjuvant chemotherapy decision‐making in the case of hormone receptor‐positive (HR+), and human epidermal growth factor receptor 2‐negative (HER2−) breast cancer with intermediate prognostic factors." (PMID 37409516, 2023). "Most participants resided in Mexico (90.30%), completed at least post‐secondary education (64%), were currently employed (45%), had been diagnosed with early‐stage breast cancer (stages 0–IIIA: 86%), and were classified as HR+/HER2− disease (66%)." (PMID 37317676, 2023). "Cyclin-dependent kinase 4 and 6 inhibitors (CDK4/6is) have transformed the treatment of hormone receptor-positive (HR+) and human epidermal growth factor receptor 2-negative (HER2−) breast cancer over the last decade." (PMID 37759823, 2023). "Previously reported studies have shown that TRAF6 is overexpressed in breast cancer, especially in TNBC patients who produce higher expression than those who carry HR+ and HER2+ breast cancer." (PMID 37746908, 2023). "Analysis of ADAM8 expression in breast cancer was extended beyond TNBC to HR−/HER2+ (n = 22), HR+/HER2− (n = 301) and HR+/HER2+ (n = 28) tumors." (PMID 37568162, 2023). "A total of 81 patients with stage II‐III breast cancers were included in this study, including 27 TNBC, 24 HR+, and 30 HER2+." (PMID 36073303, 2022). "There has been a steady increase in the use of NACT for patients with breast cancer, with the highest administration of NACT for patients with HER2+ and TNBC, administered approximately twice as often compared to patients with HR+/HER2− disease." (PMID 35877249, 2022). "As unexpected, most patients with HR+/HER2‐, early‐stage breast cancer were also treated with aggressive chemotherapy in this study while chemotherapy is considered to have low clinical benefits in this population." (PMID 34390318, 2022). "Hormone receptor-positive (HR+), HER2-negative (HER2−) is the most common breast cancer subtype (approximately 75% of all breast cancer cases)." (PMID 36358784, 2022). "The most frequent tumor subtype is hormone receptor-positive (HR+), HER2-negative (HER2−) early breast cancer (eBC)." (PMID 36358784, 2022). "This was an observational retrospective cohort study of patients with electronic medical records from January 2010 to August 2018 treated for HR+, HER2− early breast cancer at Sarah Cannon sites in the United States (US)." (PMID 35524219, 2022). "Abemaciclib plus fulvestrant showed an increase in progression free survival in a study of 669 women with HR+, HER2− breast cancer that had progressed while receiving neoadjuvant or adjuvant endocrine therapy." (PMID 34771508, 2021). "Guidelines for hormone receptor-positive (HR+), HER2-negative (HER2−) breast cancer, which constitutes the majority of diagnosed early breast cancer (EBC), generally mandate adjuvant treatment after surgery." (PMID 34575612, 2021). "PALOMA-3 examined 521 patients with metastatic hormone receptor positive (ER+ or PR+, collectively HR+), HER2− breast cancer that had disease progression after hormonal therapy (p < 0.00001)." (PMID 34771508, 2021).
breast cancer (continued). "This impressive sales forecast is high primarily because Enhertu® can be used in several subsets of breast cancer (HER2+, HR+/HER2-, and triple-negative) and it has an extended treatment duration." (PMID 34641391, 2021). "The MONARCH-2 and MONARCH-3 studies examined a third CDK4/6 inhibitor, abemaciclib, in the context of HR+, HER2− breast cancer." (PMID 34771508, 2021). "Triple-negative breast cancer subtype (TNBC) comprised 37% of the cohort, while HR+/HER2, HR+/HER2+, and HR-/HER2+ accounting for 22.2%, 14.8% and 7.4%, respectively." (PMID 34650924, 2021). "The prognostic or predictive value of commonly used multigene assays in young patients with hormone receptor-positive (HR+), human epidermal growth factor receptor 2-negative (HER2−) early breast cancer is unclear." (PMID 33708625, 2021). "Hormone receptor-positive (HR+), HER2-negative (HER2−) breast cancer (BC) accounts for over 70% percent of all breast cancer cases." (PMID 34471951, 2021). "MONALEESA-3 examined the combination of ribociclib with fulvestrant in as study of 484 HR+, HER2− patients that had received up to one line of antiestrogen therapy for advanced breast cancer." (PMID 34771508, 2021). "Based on the excellent distinguishing capability in HR+/HER2− subgroup, this model provides mechanism tips for osseous metastasis preference of HR+/HER2− subtype breast cancer." (PMID 34187256, 2021). "CDK 4/6 inhibitors that have been FDA-approved for the treatment of HR+, HER2− breast cancer (palbociclib, abemaciclib, ribociclib) are also being examined for their efficacy in the treatment of HER2+ disease, with numerous ongoing clinical trials." (PMID 34771508, 2021). "In MONARCH 3, continuous dosing of abemaciclib with an aromatase inhibitor (AI) conferred significant clinical benefit to postmenopausal women with HR+, HER2− advanced breast cancer." (PMID 34158513, 2021). "To further evaluate the effects of dual HER2 blockade, we performed several experiments in 3 HER2+ breast cancer cell lines (BT474, which is HR+, SKBR3 and HCC1954, which are HR-negative) and 1 HER2-negative cell line (MCF7, which is HR+)." (PMID 31959756, 2020). "To this end, we used the MCF7 cell line, a well-established in vitro model of invasive luminal A subtype of breast cancer with HR+/HER2- phenotype, which has been useful to dissect breast cancer mechanisms." (PMID 32728097, 2020). "Twenty breast cancer PDX models were generated from different molecular subtypes (overall success rate, 17.5%; 3.6% for HR+/HER2−, 21.4% for HR+/HER2+, 21.9% for HR−/HER2+ and 22.5% for triple-negative breast cancer (TNBC))." (PMID 31018595, 2019). "Data-driven techniques using receptor (HR and HER2) subtypes, host factors and metastatic potential from the SEER dataset identified novel unexpected endophenotypes of breast cancer and suggest the need for better classification using deeper models." (PMID 31116801, 2019). "HIF1A protein is also expressed at high levels in SKBR3 compared with the other breast cancer cell lines, MDA-MB-231 (TNBC) and T47D (HR+/HER2−), under normal culture conditions." (PMID 31018595, 2019). "PIK3CA plays important role in breast cancer treatment, the FDA on May 2019 approved alpelisib (Piqray tablets) to be used in combination with fulvestrant (endocrine therapy) for the treatment of postmenopausal women, and men, with HR+, HER2-, PIK3CA-mutated, advanced or metastatic breast cancer." (PMID 31554385, 2019). "Two-hundred twenty-four HR+ and HER2- breast cancer patients were included in the study with 202 (90.2%) of the patients diagnosed with no metastasis during the development of their breast cancer and 185 (82.6%) treated with adjuvant chemotherapy." (PMID 29796180, 2018). "HRQoL was consistently maintained from baseline in postmenopausal women with HR+, HER2− advanced breast cancer receiving ribociclib plus letrozole and was similar to that observed in the placebo plus letrozole arm." (PMID 29654415, 2018).
breast cancer (continued). "Determine the efficacy and safety of first-line ribociclib plus letrozole in elderly patients with HR+, HER2− advanced breast cancer." (PMID 29058175, 2018). "In the current pre-specified analysis of the MONALEESA-2 trial, ribociclib plus letrozole demonstrated clinical efficacy and manageable tolerability in elderly patients with HR+, HER2− advanced breast cancer." (PMID 29058175, 2018). "Recent data have also shown promising results for CDK4/6 inhibitor-based regimens in patients with HR+, HER2− breast cancer who received prior single-agent endocrine therapy." (PMID 29164421, 2018). "Results from this subgroup analysis of the MONALEESA-2 trial demonstrate that ribociclib plus letrozole provides a valuable first-line therapy option for women who present with de novo HR+, HER2− advanced breast cancer at diagnosis." (PMID 29164421, 2018). "In conclusion, combining ribociclib with letrozole provided clinically meaningful improvements in progression-free survival, overall response rates, and clinical benefit rates and was well tolerated in patients with de novo advanced HR+, HER2− breast cancer." (PMID 29164421, 2018). "Addition of ribociclib to letrozole is a valid therapeutic option for elderly patients with HR+, HER2− advanced breast cancer in the first-line setting." (PMID 29058175, 2018). "Ribociclib plus letrozole improved progression-free survival vs placebo plus letrozole and was well tolerated in postmenopausal women with HR+, HER2− de novo advanced breast cancer." (PMID 29164421, 2018). "Here, we present a summary of the large body of evidence supporting the clinical value of the 21-gene test to guide systemic adjuvant treatment decisions in patients with HR+, HER2-negative, N+ breast cancer." (PMID 30155517, 2018). "Of the 348 women who received endocrine therapy alone, 110 had HR+, HER2-negative, pN1 breast cancer." (PMID 30155517, 2018). "Currently, endocrine therapy is recommended as initial therapy for patients with HR+, HER2− advanced breast cancer." (PMID 28183331, 2017). "Safety data were consistent with the known safety profile of dovitinib, with no new safety concerns identified with the use of dovitinib in combination with fulvestrant in patients with HR+, HER2− advanced breast cancer." (PMID 28183331, 2017). "One hundred and forty-three patients (66%) presented with HR+/HER2− breast cancer, 51 (24%) with triple-negative breast cancer, and 14 (6%) with HER2-overexpressing breast cancer." (PMID 28027327, 2016). "Administration of the mTor inhibitor Everolimus has therefore been studied extensively in women with HR+, HER2+ or TNBC breast cancer." (PMID 26205886, 2015). "We report the case of a 75-year-old woman with HR+/HER2-low (HER2 2+/FISH– at diagnosis, HER2–0 at recurrence) advanced breast cancer who developed multiple lymph node metastases and a large pleural effusion after progression on endocrine therapy plus a CDK4/6 inhibitor." (PMID 41487578, 2025). "Use of adjuvant chemotherapy following resection of hormone receptor positive, human epidermal growth receptor 2 negative (HR+/HER2-) breast cancer is guided by gene expression profiles (GEP)." (PMID 40347583, 2025). "As such, ET is a standard adjuvant treatment for HR+, HER2– early-stage breast cancer." (PMID 39774684, 2025). "Fluvestant is indicated for HR+ and HER2- advanced breast cancer in postmenopausal women." (PMID 40136358, 2025). "However, about one in three women presenting with HR+, HER2− breast cancer have lymph node involvement." (PMID 38308000, 2024). "HER2+ metastasis breast cancer (MBC) and other breast cancer subtypes have not demonstrated as much Trop-2 expression as HR+/HER2- breast cancer." (PMID 39456611, 2024).